PTPRJ (protein tyrosine phosphatase receptor type J)
Diseases named in the same sentence as PTPRJ in open-access papers (continued):
Sharing a sentence is not in itself a finding about the gene and the disease.
tumor (continued). "PTPRJ, a receptor protein tyrosine phosphatase strongly downregulated in human cancer, displays tumor suppressor activity by negatively modulating several proteins involved in proliferating signals." (PMID 29805737, 2018). "Here, we confirmed that the PTPRJ short isoform (named sPTPRJ) is a soluble protein secreted into the supernatant of both endothelial and tumor cells." (PMID 28052032, 2017). "From the six signature proteins (HLA-A, CFH, CD44, PTPRJ, HP, and CDH5), only CD44 has been previously associated with CRC prognosis in tumor specimens from 74 patients that were assayed by immunohistochemistry." (PMID 26253080, 2015). "This anti-tumour activity of PTPRJ has also been demonstrated in In vitro experiments, using agonist peptides of PTPRJ and the oncogenic silencing of PTPRJ expression by microRNA-328 expression." (PMID 24885312, 2014). "Since it has a reduced expression in some malignant tumors it is considered as a putative tumor suppressor, which is further substantiated by its cell density-mediated regulation, and reversion of the transformed phenotype when PTPRJ function is restored." (PMID 25532119, 2014). "PTPRJ has been widely accepted as an epithelial cell expressed gene and has been proposed to be a tumor suppressor in this cell type." (PMID 23840844, 2013). "Consistent with the tumor data, PTPRJ protein was detected in all cell lines, with expression levels varying from highest in T47D and MDAMB231 cells, to lower in MCF7, ZR751 and MCF10A cells." (PMID 22815804, 2012). "A reduction in the proliferation, survival and tumorigenicity of several cell types upon ectopic expression of PTPRJ further suggests a tumor suppressor role for this protein." (PMID 22815804, 2012). "While not exclusively focused on angiogenesis, a clinical trial includes the investigation of PTPRJ genetic variations in cancer patients, which may provide insights into its role in tumor angiogenesis and potential therapeutic targeting." (PMID 38999976, 2024). "In addition, by bioinformatics methods, we found that PTPRJ expression was low in tumor tissues and that its expression was negatively correlated with miR-4443 expression." (PMID 36578050, 2022). "PTPRJ overexpression in diverse cancer cell lines was shown to exert a negative regulatory effect on cell proliferation, migration, differentiation, and cell adhesion, as well as on transformation, and is therefore considered to be a tumor suppressor." (PMID 36611803, 2022). "PTPRJ has been nominated as a tumor suppressor in other cancers." (PMID 35706047, 2022). "PTPRJ might be involved in malignancies at different levels acting both as a tumor suppressor, but also in the regulation of antitumoral T-cell activity." (PMID 33810219, 2021). "In approximately 20% tumors, mutations in PTPRJ (protein tyrosine phosphatase, receptor type J), a putative tumor suppressor gene not previously shown to have frequent inactivating point mutations in cancer, was observed." (PMID 31717496, 2019). "PTPRJ substrates that may mediate its tumor suppressive potential include ERK1/2, Akt, various receptor tyrosine kinases, and Src kinases." (PMID 30188888, 2018). "PTPRJ is a receptor protein tyrosine phosphatase with tumor suppressor activity." (PMID 28052032, 2017). "It is likely that the upregulation of these pathways in cells with functional PTPRJ are the consequence of the activation of tumour suppressor activities, such as controlling cell proliferation and proapoptotic signalling through dephosphorylation of VEGFR, MAPK and PI3K pathways." (PMID 24885312, 2014). "PTPRJ is found in a wide range of cell types and evidence for a tumour suppressor role has been indicated due to its reduced expression in some malignant tumours, its regulation by cell density, and the reversion of the transformed phenotype when PTPRJ function is restored." (PMID 23840844, 2013).
tumor (continued). "Therefore, the results reported here contribute to shed lights on PTPRJ signaling in cancer cells: moreover, our findings also support the development of a novel anticancer therapeutic approach by targeting the pathway of PTPRJ that is usually downregulated in highly malignant human neoplasias." (PMID 29805737, 2018). "However, in areas where the tumor retained partial glandular/tubular architecture, PTPRJ delineated the lumina (black arrowheads) i.e. showed the apical staining of luminal cells observed in normal breast samples or in normal areas of tissue adjacent to the tumor (grey arrowheads)." (PMID 22815804, 2012). "BRMS1L, CPEB3, KIF3B, NEDD4L, PTPRJ, and RBL2 were significantly downregulated in tumor samples compared to controls." (PMID 40943553, 2025). "In cervical cancer cell lines, PTPRJ inactivates the Janus kinase 1 (JAK1)/STAT3 pathway, impeding proliferation and tumor formation." (PMID 38999976, 2024). "Further studies revealed that PTPRJ is involved in the hepatocyte growth factor (HGF) tyrosine kinase receptor c-Met, which affects the pro-tumor capacity of p38." (PMID 36611803, 2022). "Protein tyrosine phosphatase receptor type J (PTPRJ, DEP1) is a tumour suppressor gene that negatively regulates such processes as angiogenesis, cell proliferation and migration and is one of the genes important for tumour development." (PMID 30661225, 2019). "Protein tyrosine phosphatase receptor type J (PTPRJ, DEP1) is described as a tumour suppressor gene that negatively regulates angiogenesis, cell proliferation and migration and therefore is involved in tumour progression in some human cancers." (PMID 30661225, 2019). "Density-enhanced phosphatase-1 (DEP-1/PTPRJ) is a regulator of hematopoietic cell functions, and a candidate tumor suppressor." (PMID 23650535, 2013). "We also know from investigations of the relationship between PTPRJ and EGFR, that one proposed tumour suppressive mechanism for DEP-1 is the inactivation and retention of EGFR at the cell membrane and therefore the abrogation of EGF-induced signaling." (PMID 22815804, 2012). "Also, we identified novel predicted tumor-suppressive ligands (SLIT3, DCN, CCN3, THBS1, INHA and INHBA), proteins (DNASE1L3, SULF1, PTEN, OAS1, and DAB2IP), and receptors (P2RX4, CDHR2, PTPRJ, and PTPRH) in MSC1 cells." (PMID 40564222, 2025). "Considering that CD4+ T cells play a key role in tumor immunity and that the inhibition of TCR signaling may affect anti-tumor activity in CD4+ T cells, we explored whether PTPRJ could serve as a therapeutic target for enhanced peripheral immunity." (PMID 38735538, 2024). "Finally, other proteins identified in our 4 × 4 proteomic comparison of PDAC vs HC organoid EVs with more variability in the larger PDAC panel (PTPRJ, MUC16, TAOK1) are also reported markers of tumor-development in several cancer models." (PMID 35241737, 2022). "Multivariate analysis adjusting for tumor grade however, showed lack of independence of PTPRJ expression as a prognostic factor in this data series (p = 0.293)." (PMID 22815804, 2012). "Moreover, the relationship between miR-4443, PTPRJ, and tumor radiotherapy has not been reported." (PMID 36578050, 2022).
cancer (42 papers, 2012 to 2025). A tumor composed of atypical neoplastic, often pleomorphic cells that invade other tissues. "Recent studies, through whole-exome sequencing of the human cancer genome, have shown that PTPRJ is mutated in a variety of cancers." (PMID 36611803, 2022). "In vitro treatment of EGFR-driven cancer cells with those peptide agonists was shown to decrease PTPRJ self-association, enhance its activity on EGFR, and ultimately inhibit EGFR-driven cancer cell migration." (PMID 36452504, 2022). "CD148 is a member of the receptor-type protein tyrosine phosphatase family encoded by the PTPRJ gene and has controversial impacts on cancers." (PMID 32201537, 2020). "PTPRJ loss of heterozygosity (LOH) has been reported in several cancers such as colon, breast, thyroid, meningioma, non-Hodgkin lymphoma and cervical carcinoma." (PMID 30661225, 2019). "Five articles describing the association between PTPRJ Arg326Gln and Gln276Pro polymorphisms in six different cancers (breast, colorectal, oesophagus, head and neck, lung and thyroid) were included in the analysis." (PMID 30661225, 2019). "Here, we present the first report of recurrent somatic truncating mutations in PTPRJ in a naturally occurring cancer." (PMID 30188888, 2018). "More recently PTPRJ was identified in phosphotome screening as a potent negative regulator of Akt activation in Ras-mutated cancer cells and it directly desphosphorylates ERK1/2." (PMID 22815804, 2012). "Specific genes were highlighted for Hallmarks of Cancer NAG-related genes (PTPRJ and NDUFS) were linked to cell proliferation and growth; IGC genes (GNAI2, RHOA, MAPKAPK3, MST1R) to genomic instability, metastasis, and arrest of cell death; and DGC genes to energy metabolism and immune evasion." (PMID 40028213, 2025). "Furthermore, several studies have implicated the PTPRJ polymorphisms in susceptibility to human cancers, which cause missense mutations in the extracellular domain of CD148." (PMID 34791835, 2022). "For example, mutations disrupting the glycine zipper motif in PTPRJ reduce its oligomerisation, which in turn enhances phosphatase activity and suppresses EGFR-driven cancer phenotypes." (PMID 40941028, 2025). "Top expressed cancer-implicated gene targets for each TF converged on notable genes involved in cell signaling (SMAD3, PTPRJ), BCL6 regulation (FBXO11, BCOR), and transcriptional regulation (RUNX1, ERG, CUX1)." (PMID 38116118, 2023). "PTPRJ is a receptor protein tyrosinase, and PTPRJ-pep19.7 is capable of binding and activating PTPRJ to bring about anti-cancer effects." (PMID 36430160, 2022). "The aim of this review is to highlight the PTPRJ mechanisms explored in cancer, metabolic diseases, axon guidance, and neuroinflammation." (PMID 36611803, 2022). "Here, we reviewed and compiled the most current knowledge on the structure, expression, and regulation of PTPRJ and its contribution to cellular phagocytosis, axonal projection, cancer, and metabolic diseases." (PMID 36611803, 2022). "To better understand the mechanisms of CD98hc protein downregulation in PTPRJ-overexpressing A549 cancer cells, we first evaluated CD98hc mRNA expression by real time-PCR." (PMID 29805737, 2018). "Here, in the attempt to further shed lights on the PTPRJ protein network and its role in cancer, we identified several novel putative candidate PTPRJ protein partners by using a proteomic-based approach." (PMID 29805737, 2018). "PTPRJ expression is decreased in many cancer cells and its restoration is able to suppress the malignant phenotype." (PMID 28052032, 2017). "Where the tubular architecture was lost, diffuse cytoplasmic staining of PTPRJ was observed, and this was particularly prominent where there were nests of carcinoma cells (white arrows, and 2F)." (PMID 22815804, 2012).
cancer (continued). "In addition, recent studies have shown that PTPRJ acts to inhibit cancer cell proliferation by regulating the expression of mRNA and DNA methylation and is regulated by a number of microRNA, such as miR-328, miR-155, etc.." (PMID 36611803, 2022). "Extended genetic screening revealed additional germline variants within the cancer-associated NBN, MC1R, and PTPRJ genes in non-LS branches of the family in which several members also had cancer diagnoses." (PMID 36612224, 2022). "As has been demonstrated, PTPRJ is expressed in various types of cells (e.g. epithelial, haematopoietic and endothelial cells and many cancer cell lines), and thus its effect on different cancer types seems to be indisputable." (PMID 30661225, 2019). "The most commonly mutated gene in this cohort was the putative tumor suppressor gene PTPRJ, not previously shown to have frequent inactivating point mutations in cancer." (PMID 30188888, 2018). "Indeed, miR-328 expression leads to PTPRJ downregulation through increasing cell proliferation of cancer cell lines such as HeLa and SKBr3." (PMID 29805737, 2018). "Interestingly, PTPN11 and PTPRJ share around 24 gene interactions, which enriched important pathways in cancer such as ERBB signalling pathway, cytokine-cytokine interactions pathway, JAK/STAT signalling pathway and others." (PMID 24885312, 2014). "Furthermore, multiple receptor tyrosine kinases (RTKs) as substrates of PTPRJ are probably a potential therapeutic target for many types of diseases, such as cancer, neurodegenerative diseases, and metabolic diseases, by inhibiting their phosphorylation activity." (PMID 36611803, 2022). "Given that TSP-1 is produced by various cell types in pathological conditions, including endothelial or cancer cells, TSP-1 appears to act as a ligand for PTPRJ in such conditions." (PMID 38999976, 2024). "Thus, the interaction of homodimers of PTPRJ could be a new approach to treating certain cancers." (PMID 36611803, 2022). "However, a significantly higher upregulation of PTPRJ has been reported in GBM, suggesting that the regulatory role of PTPRJ may be more complex, and further research is needed to explore the role of PTPRJ in different cancers and at different stages of cancer." (PMID 36611803, 2022). "Multiple cancer survival-related genes were found in these genes, including CDH17, PTPRJ, SLC16A14, TMTC2, and NOTCH4." (PMID 32426342, 2020). "Additionally, terms related to signaling axes that are commonly hijacked by cancer cells, such as terms related to ALK, TROP2, and TOB1, which is a growth-suppressive factor, and EGFR and ERBB (leading genes DAB2IP and PTPRJ) were enriched in both analyses." (PMID 40564222, 2025). "While no PTPRJ copy number variants (CNVs) were found in > 2650 cancer-free controls, the screening of an additional cohort of ~1500 CRC patients detected a 564-kb duplication in a 39-year-old CRC patient, also causing PTPRJ promoter methylation." (PMID 32585810, 2020). "It was also reported that PTPRJ agonist nonapeptide led to reduction of cell proliferation and promotion of apoptosis in cancer cell lines and also inhibited tube formation in an in vitro experiment." (PMID 30661225, 2019). "Furthermore, we identified cancer-related genes aberrantly expressed in ccRCC (BRMS1L, CPEB3, DNAJB9, KIF3B, NFIB, PTPRJ, RBL2) and targeted by members of the miR-106b-25 cluster, suggesting that their dysregulation may be driven by these miRNAs." (PMID 40943553, 2025). "Therefore, we expected that protein No. 2 might combine with PTPRJ to bring about an anti-cancer effect." (PMID 36430160, 2022).
infection (6 papers, 2013 to 2025). The state of being infected such as from the introduction of a foreign agent such as serum, vaccine, antigenic substance or organism. "Next, we also demonstrated that endogenous CD98hc co-immunoprecipitated ectopic PTPRJ protein overexpressed in A549 cells twenty-four hours after infection with a recombinant adenovirus carrying a wild-type PTPRJ cDNA at MOI30." (PMID 29805737, 2018).
metabolic disease (2 papers, 2013 to 2022). A congenital disorder (due to inherited enzyme abnormality) or acquired (due to failure of a metabolically important organ) disorder resulting from an abnormal metabolic process. "Mechanism of protein tyrosine phosphatase receptor type J (PTPRJ) in metabolic disorders." (PMID 36611803, 2022). "Currently, PTP inhibitors have been explored in clinical trials, such as one trial examining the role of inhibitors of PTP1B in metabolic diseases, but inhibitors of PTPRJ have not yet been identified, which may be an indication for future research." (PMID 36611803, 2022).
colon (1 paper, 2022). "A number of food nutrients, such as butyrate, green tea, and apple polyphenols, have been shown to upregulate endogenous PTPRJ mRNA transcription and PTPRJ protein expression and may act as chemoprotective foods against colon carcinogenesis." (PMID 36611803, 2022).
neurodegenerative disease (1 paper, 2022). A disorder of the central nervous system characterized by gradual and progressive loss of neural tissue and neurologic function. "Together, these experiments suggested that PTPRJ may have an essential function in microglia-mediated neuroinflammation-associated diseases, and further studies could be focused on the involvement of PTPRJ in inflammation-related neurodegenerative diseases." (PMID 36611803, 2022).
PTPRJ also shares sentences with these, for which no sentence is quoted: Crohn disease (3 papers); type 2 diabetes (3); Insulin resistance (2); Salmonella Infections (2); acute monocytic leukemia (1); adenoma (1); arteriosclerosis (1); autoimmune disease (1); autoimmune inner ear disease (1); autoimmune thyroid disease (1); Autoimmunity (1); bacterial infection (1); brain disorder (1); Cachexia (1); cardiomyopathy (1); cardiovascular disease (1); Chlamydia infection (1); dengue (1); diabetes (1); endometrial cancer (1); epidermoid carcinoma (1); esophageal squamous cell carcinoma (1); hereditary colorectal cancer (1); hereditary thrombocytopenia (1); Hyperkalemia (1); hypotension (1); hypothyroidism (1); idiopathic pulmonary fibrosis (1); invasive carcinoma (1); iron deficiency (1).
A further 10 diseases each share a sentence with PTPRJ in 1 paper.